MTF2 (metal response element binding transcription factor 2)
Description:
Polycomb group (PcG) protein that specifically binds histone H3 trimethylated at 'Lys-36' (H3K36me3) and recruits the PRC2 complex, thus enhancing PRC2 H3K27me3 methylation activity. Regulates the transcriptional networks during embryonic stem cell self-renewal and differentiation (By similarity). Promotes recruitment of the PRC2 complex to the inactive X chromosome in differentiating XX ES cells and PRC2 recruitment to target genes in undifferentiated ES cells (By similarity). Required to repress Hox genes by enhancing H3K27me3 methylation of the PRC2 complex (By similarity). In some conditions may act as an inhibitor of PRC2 activity: able to activate the CDKN2A gene and promote cellular senescence by suppressing the catalytic activity of the PRC2 complex locally (By similarity). Binds to the metal-regulating-element (MRE) of MT1A gene promoter (By similarity).
Synonyms: PCL2; M96; TDRD19A; dJ976O13.2
Tractability: PROTAC: UniProt records ubiquitination sites on it; ubiquitination databases record sites on it; its protein half-life has been measured.
Gene: Protein-coding gene on chromosome 1 (93,079,235 to 93,139,079, forward strand). Ensembl gene ENSG00000143033.
Subcellular location: Nucleus
Subcellular location (Human Protein Atlas): Nucleoplasm
Pathways (Reactome):
Gene expression (Transcription): PRC2 methylates histones and DNA
Gene Ontology:
Molecular function: transcription corepressor binding; chromatin binding; histone H3K36me3 reader activity; RNA polymerase II transcription regulatory region sequence-specific DNA binding
Biological process: epigenetic regulation of gene expression; heterochromatin formation; negative regulation of gene expression, epigenetic; negative regulation of transcription by RNA polymerase II; segment specification; stem cell differentiation; stem cell population maintenance
Cellular component: cytoplasm; nucleoplasm; nucleus; ESC/E(Z) complex
Genetic constraint (gnomAD): Loss-of-function variants: 10 observed, 58.67 expected, observed/expected ratio (o/e) 0.17, 90% interval 0.1 to 0.29. The upper end of that interval is the gene's LOEUF score, 0.29, which puts it in group 1 of 6, group 1 being the genes least tolerant of losing a copy. Missense variants: 435 observed, 651.58 expected, observed/expected ratio (o/e) 0.67, 90% interval 0.62 to 0.72. Synonymous variants: 193 observed, 215.83 expected, observed/expected ratio (o/e) 0.89, 90% interval 0.79 to 1.01.
Homologues: Orthologues: chimpanzee MTF2 (100% identical), macaque MTF2 (99% identical), pig MTF2 (99% identical), rabbit MTF2 (99% identical), mouse Mtf2 (98% identical), rat Mtf2 (96% identical), dog MTF2 (90% identical), guinea pig MTF2 (78% identical), tropical clawed frog mtf2 (75% identical), zebrafish mtf2 (66% identical), Drosophila melanogaster Pcl (29% identical). Paralogues in human: PHF19 (44% identical), PHF1 (38% identical).
Diseases named in the same sentence as MTF2 in open-access papers:
MTF2 is named in the same sentence as 43 diseases in open-access papers, as found by Europe PMC text mining. Sharing a sentence is not in itself a finding about the gene and the disease. The quoted sentences say what the papers report.
acute myeloid leukemia (4 papers, 2022 to 2024). Acute myeloid leukemia (AML) is a group of neoplasms arising from precursor cells committed to the myeloid cell-line differentiation. "In acute myeloid leukemia, a reduced level of MTF2 has been associated with increased chemotherapy resistance, thus resulting in a worse prognosis." (PMID 37107696, 2023). "In addition, MTF2 deficiency could predict refractory acute myeloid leukemia at initial diagnosis." (PMID 35734428, 2022). "MTF2 has been suggested as a therapeutic target for myeloma and Acute Myeloid Leukemia." (PMID 39480826, 2024).
breast carcinoma (4 papers, 2020 to 2025). "More recently, a similar association between low MTF2 expression and increased resistance to chemotherapeutics has also been reported in basal-like breast cancer cells (BLBC)." (PMID 37895228, 2023). "A similar link between low MTF2 expression and increased resistance to chemotherapeutics has been shown in basal-like breast cancer cells." (PMID 37107696, 2023). "Notably, MTF2 was expressed lowly in breast cancer tissue samples at different clinical stages, with a decreasing trend towards the higher stages of the disease, suggesting its role in cancer initiation and progression." (PMID 37895228, 2023). "Moreover, p21, a cyclin-dependent kinase inhibitor, was increased under such conditions, pointing to the role of MTF2 in regulating the cell cycle in breast cancer." (PMID 37895228, 2023). "In fact, this group revealed that the decreased expression levels of Mtf2 and core PRC2 subunits resulted in breast cancer cells surviving cytotoxic treatment." (PMID 37895228, 2023). "In contrast to the role of MTF2 as a tumour suppressor in AML and breast cancer, MTF2 demonstrates oncogenic activity in other malignancies." (PMID 37895228, 2023). "However, since MTF2 regulates MDM2 expression and/or activity in AML and breast cancer, we integrated MDM2 transcript levels into our analysis." (PMID 37895228, 2023). "Our results that MTF2 represses CCND1 expression in MDA-MB-231 may help explain the recent reports that low MTF2 expression leads to increased chemotherapeutic resistance in leukemia and downregulation of MTF2 was correlated with poorer clinical outcomes in breast cancer." (PMID 39903505, 2025).
glioblastoma (4 papers, 2020 to 2025). The most malignant astrocytic tumor (WHO grade IV). "MTF2 has also been associated with the development and progression of glioblastoma, an aggressive brain tumour." (PMID 37895228, 2023). "In this study, immunohistochemistry results from human glioma samples corroborated the results from the TCGA data analysis showing elevated MTF2 expression in glioblastoma multiforme (GBM) and lower-grade glioma." (PMID 37895228, 2023). "Our findings demonstrate that PCIF1 selectively represses MTF2 translation, leading to tumour progression, which aligns with the role of m6Am modifications as previously reported in several cancers, such as colorectal cancer, glioblastoma and gastric cancer." (PMID 40156159, 2025).
glioma (4 papers, 2020 to 2025). A benign or malignant brain and spinal cord tumor that arises from glial cells (astrocytes, oligodendrocytes, ependymal cells). "We then mapped SUZ12 and MTF2 signal in H3.3K27M glioma cells at sites of K27M enrichment (as H3.1K27M cells only have the K27M epitope dispersed across the genome)." (PMID 32902381, 2020). "To investigate the relationship between PRC2 components, H3K27me3, and K27M mutant histones in chromatin, we profiled two Polycomb proteins – SUZ12 of the PRC2 complex and the MTF2 transcription factor – in VUMC and in K27M mutant glioma lines." (PMID 32902381, 2020).
hepatocellular carcinoma (4 papers, 2020 to 2023). A malignant tumor that arises from hepatocytes. "We performed Gene Ontology (GO) enrichment analysis on a TCGA cohort of cancers with low (AML, thymoma, and uterine carcinosarcoma) and high (hepatocellular carcinoma and sarcoma) MTF2 expression levels." (PMID 37895228, 2023). "Comparably, in cancer types with high MTF2 transcript levels, hepatocellular carcinoma and sarcoma also had low similarity with each other." (PMID 37895228, 2023). "In summary, the Kaplan–Meier analyses confirm published AML and hepatocellular carcinoma studies while underscoring potential prognostic or mechanistic roles of MTF2 in thymoma, uterine carcinosarcoma, and sarcoma." (PMID 37895228, 2023). "Collectively, these findings indicate the oncogenic property of MTF2 in hepatocellular carcinoma." (PMID 37895228, 2023). "MTF2 has also been reported to induce the progression and metastasis of hepatocellular carcinoma (HCC)." (PMID 37895228, 2023). "In hepatocellular carcinoma (HCC), the high expression of MTF2 has been linked to the activation of EMT-related pathways, whereby Snail was identified as an important downstream effector of MTF2, further supporting that MTF2 can act as an oncogene in some cancer types." (PMID 37107696, 2023). "MTF2 (metal regulatory transcription factor 2), for example, was shown to induce EMT by transcriptionally activating Snail in hepatocellular carcinoma, whereas PHF8 (PHD finger protein 8) is an enzyme that demethylates the H3K9, H3K27, and H4K20 lysine residues." (PMID 32831131, 2020).
myeloma (4 papers, 2021 to 2024). "Loss of either WDR26 or MTF2 by genetic ablation significantly impeded the growth of myeloma cells in vitro and in vivo via mouse xenograft assays, extending the survival of the xenografted mice." (PMID 37895228, 2023). "For example, in the blood cancer multiple myeloma, MTF2 and PHF19 were found to be upregulated compared to plasma cells from healthy individuals and were associated with high-risk disease." (PMID 37895228, 2023). "Studies have found that MTF2, as an accessory subunit of PRC2, is an important target for the treatment and prevention of myeloma." (PMID 36713456, 2022). "Rigorous clinical and biological validation of these genes led to the discovery of two novel myeloma genes: WDR26 (WD repeat-containing protein 26) and MTF2 (metal response element binding transcription factor 2)." (PMID 34876184, 2021). "Further investigation is needed to unravel the oncogenic networks involving MTF2, PHF19, and WDR26 in myeloma, as this could reveal novel opportunities for targeted molecular treatments and prevention strategies." (PMID 37895228, 2023). "Moreover, a forward genetics screen identified MTF2 and WDR26 as drivers of poor survival rates in multiple myeloma." (PMID 37895228, 2023). "MTF2, an ancillary subunit of the polycomb repressive complex 2 (PRC2), is a close functional relative of PHD finger protein 19 (PHF19) which is currently emerging as an important driver of myeloma." (PMID 34876184, 2021).
anemia (3 papers, 2018 to 2023). A reduction in the number of red blood cells, the amount of hemoglobin, and/or the volume of packed red blood cells. "The loss of Mtf2 has been shown to be embryonic lethal by E15.5, with observations of severe anemia and growth retardation." (PMID 34848733, 2021). "The resulting de-repression of transcriptional and signaling networks blocks definitive erythroid development, culminating in Mtf2−/− embryos dying by e15.5 due to severe anemia." (PMID 29736258, 2018). "As detailed in the next section, Mtf2−/− embryos died due to severe anaemia." (PMID 37895228, 2023). "Mtf2−/− embryos also displayed growth defects and haemorrhaging, although these phenotypes may be secondary effects of anaemia." (PMID 37895228, 2023). "Mtf2−/− embryos die at e15.5, displaying growth defects, hemorrhage and severe anemia." (PMID 29736258, 2018).
leukemia (3 papers, 2022 to 2025). A malignant (clonal) hematologic disorder, involving hematopoietic stem cells and characterized by the presence of primitive or atypical myeloid or lymphoid cells in the bone marrow and the blood. "Previous research has also indicated that MTF2 downregulation is linked to increased cell proliferation and metastasis in cancers like leukaemia and colorectal cancer, where its loss leads to chromatin instability and the activation of oncogenic pathways." (PMID 40156159, 2025). "Dysregulation of MTF2 has been implicated in tumourigenesis in diverse cancers, including leukaemia and colorectal cancer, where its loss leads to aberrant gene expression and chromatin instability." (PMID 40156159, 2025). "Eliminating MDM4 and MDM2 by MMRi62 hits the key drug targets in AML because MDM4 is a pervasive driver of leukemogenesis in multiple mouse leukemia models, and MDM2 overexpression induced by MTF2 loss is a mediator for refractory AML." (PMID 35992795, 2022).
colorectal cancer (2 papers, 2024 to 2025). A primary or metastatic malignant neoplasm that affects the colon or rectum. "MTF2 is upregulated in colorectal carcinoma (commonly arising from Lynch Syndrome) and contributes to copper homeostasis which is dysregulated in many cancers." (PMID 39480826, 2024).
diffuse large B-cell lymphoma (2 papers, 2020 to 2023). "In contrast, transcript levels of both MTF2 and MDM2 are elevated in diffuse large B-cell lymphoma and esophageal carcinoma, whereas both MTF2 and MDM2 transcripts are down-regulated in malignant ovarian cancer (serous cystadenocarcinoma)." (PMID 37895228, 2023).
retinoblastoma (2 papers, 2023 to 2024). A malignant tumor that originates in the nuclear layer of the retina. "Using both gain- and loss-of-function perturbations in two retinoblastoma cell lines, they demonstrated that MTF2 is a target of the lncRNA colon cancer-associated transcript 1 (CCAT1)/miR-218-5p regulatory axis." (PMID 37895228, 2023). "Specifically, they found that MTF2 is overexpressed in retinoblastoma." (PMID 37895228, 2023). "However, whether MTF2 is inhibited by miR-218-5p in other cancers besides retinoblastoma remains to be explored." (PMID 37895228, 2023). "Thus, overexpression of CCAT1 led to increased MTF2 abundance with concomitant elevated EMT, cell migration, and invasion of retinoblastoma." (PMID 37895228, 2023).
sarcoma (2 papers, 2022 to 2023). A usually aggressive malignant neoplasm of the soft tissue or bone. "The strong correlation between high MTF2 levels and poor overall survival in sarcoma patients indicates that mechanistic studies of MTF2 in sarcoma are warranted." (PMID 37895228, 2023). "Mutations of each gene (LMO2, MAML3, MTF2, RBPMS, and SIRT1) in sarcoma were 6, 7, 6, 3, and 5%, respectively, with the most common changes in the mRNA expression." (PMID 35734428, 2022). "In order to reveal the association between the expressions of five TcoF-related genes (LMO2, MAML3, MTF2, RBPMS, and SIRT1) in the risk model and immune cell infiltration, the data on sarcoma from the TIMER database were collected." (PMID 35734428, 2022).
Thyroid carcinoma (2 papers, 2020 to 2023). "Notably, in addition to AML, adrenocortical carcinoma and thyroid carcinoma demonstrate decreased MTF2 levels and concomitant elevated MDM2 expression, suggesting that loss of MTF2 in adrenocortical carcinoma and thyroid carcinoma could impact disease progression and therapeutic response." (PMID 37895228, 2023).
asthma (1 paper, 2022). "MTF2, a target of hsa-miR-181a-2-3p, has been linked to the PI3K pathway in asthma and is consistent with our GO analysis where the term ‘PI3K’ was highly enriched." (PMID 36264868, 2022).
autism (1 paper, 2021). Persistent deficits in social interaction and communication and interaction as well as a markedly restricted repertoire of activity and interest as well as repetitive patterns of behavior. "We observed genes that were shared across the subgroups such as UCP2 (control, PDD-NOS, autism, and AS) or highly expressed MTF2 (PDD-NOS and AS)." (PMID 33719335, 2021). "Furthermore, we identified ASD subgroup-specific hubs, for example, GAS5|SNORD76 and MTF2 for PDD-NOS or BAZ2A and MTCO2P12|COX2 for autism." (PMID 33719335, 2021).
brain tumor (1 paper, 2010). "Good agreement was also observed on alignment with the malignant brain tumor repeat (MBT) domain of PHF20L1 (PDB 2jtf) and the metal response element-binding transcription factor 2 (PDB 2eqj)." (PMID 21072162, 2010).
breast tumor (1 paper, 2022). "The negative correlation between CTR9 and PRC2.1 facultative subunits (PHF1/MTF2/PHF19 and EPOP) at the mRNA level was also observed in 817 ER-positive primary breast tumor samples in TCGA." (PMID 35137163, 2022).
Lynch syndrome (1 paper, 2024). An autosomal dominant hereditary neoplastic syndrome characterized by the development of colorectal carcinoma and a high risk of developing endometrial carcinoma, gastric carcinoma, ovarian carcinoma, renal pelvis carcinoma, and small intestinal carcinoma. "We propose that ADNP, CHTOP, HLTF, MTF2, WAPL, and ZMYM4 are novel genes in Lynch Syndrome." (PMID 39480826, 2024).
mood disorder (1 paper, 2020). A cognitive disorder a disturbance in which the person's mood is hypothesized to be the main underlying feature. "This warrants further investigation as to whether higher levels of Mtf2 are associated with increased risk of mood disorders in humans." (PMID 30356121, 2020).
osteosarcoma (1 paper, 2022). A usually aggressive malignant bone-forming mesenchymal neoplasm, predominantly affecting adolescents and young adults. "MTF2 and RBPMS were both highly expressed in osteosarcoma tissues compared with normal osseous controls with p values of 0.0071 and 0.0234, respectively." (PMID 35734428, 2022). "The results showed that the expressions of MTF2 and RBPMS were upregulated in all osteosarcoma cell lines (MNNG/HOS, 143B, MG63, and WELL5) compared with the osteoblast cell line." (PMID 35734428, 2022). "The expressions of MTF2 and RBPMS in osteosarcoma tissues and normal osseous tissues were analyzed by IHC." (PMID 35734428, 2022). "Finally, we selected MTF2 and RBPMS for IHC validation in osteosarcoma tissues and normal osseous tissues." (PMID 35734428, 2022).
periodontitis (1 paper, 2025). An acute or chronic inflammatory process that affects the tissues that surround and support the teeth. "Jarid2 and Mtf2, involved in chromatin remodeling and gene repression, contribute to the persistent inflammatory environment and tissue destruction observed in the advanced stages of RA and periodontitis." (PMID 40076622, 2025).
prostate carcinoma (1 paper, 2020). A carcinoma that arises from epithelial cells of the prostate gland. "Together, these results indicate that, in prostate cancer, PHF19L restricts an excessive occupancy of MTF2 at chromatin, suggesting that MTF2 could be responsible for the increase in PRC2 recruitment and activity following PHF19L depletion." (PMID 32155117, 2020).
seminoma (1 paper, 2022). A radiosensitive malignant germ cell tumor found in the testis (especially undescended), and extragonadal sites (anterior mediastinum and pineal gland). "In seminoma, the PSI value of MTF2 was found to be significantly upregulated and consistent with the experimental results." (PMID 36713456, 2022).
thymoma (1 paper, 2023). A neoplasm arising from the epithelial cells of the thymus. "In thymoma patients with low MTF2, we also observed cell cycle and regulation of the apoptotic process, confirming low similarity with MTF2-low AML samples." (PMID 37895228, 2023). "Notably, PRKCD showed increased expression across MTF2-low AML, thymoma, and uterine carcinosarcoma." (PMID 37895228, 2023). "Strikingly, although thymoma tumours generally express higher levels of MTF2 than non-disease thymic tissue, “MTF2-low” thymoma patients have lower survival rates." (PMID 37895228, 2023). "In contrast, analysis of dysregulated pathways in MTF2-low uterine carcinosarcoma patients showed no significant similarity with either AML or thymoma patients." (PMID 37895228, 2023).
uterine carcinosarcoma (1 paper, 2023). A usually aggressive malignant neoplasm arising from the uterine corpus and less often the cervix. "Additionally, uterine carcinosarcoma patients within the “MTF2-low” group also have lower survival rates." (PMID 37895228, 2023).